CACNA1B (calcium voltage-gated channel subunit alpha1 B)
Diseases named in the same sentence as CACNA1B in open-access papers (continued):
Sharing a sentence is not in itself a finding about the gene and the disease.
cancer (7 papers, 2015 to 2022). A tumor composed of atypical neoplastic, often pleomorphic cells that invade other tissues. "Twelve genes were located in eight of the top-15 breakpoint regions, and six of these genes are associated with cancer (CACNA1B, IBSP, MEPE, NBEA, RELN and THSD7A)." (PMID 31249626, 2019). "Five genes were located in four of the seven breakpoint regions and three of these genes (CACNA1B, C8orf33 and KIAA0513) are associated with cancer." (PMID 31249626, 2019). "In these cancers, increases in CACNA1B expression ranged from 1.53- to 1.56-fold, with p-values from 3.25E-4 to 6.22E-4 relative to control samples." (PMID 26147197, 2015). "Previous studies have shown that CACNA1B is important for sustained neuronal firing and neurotransmitter release in neuropathic pain; however, until now, CACNA1B has not been implicated in cancer." (PMID 26147197, 2015). "The MAPK signaling pathway has been shown to be activated in many cancers that are resistant to drugs, and our study found that RPS6KA1, CACNA1B, and MAPK8IP3 were significantly enriched in the MAPK signaling pathway." (PMID 35168607, 2022). "In addition, the strict scale in the present study to only analyze the proteins detected in all examined samples ruled out some important DEPs such as cancer-related proteins, which changed dramatically during carcinogenesis, such as Cacna1b, Col15a1, Hmgcr, Zfp82, and Znrd1-as." (PMID 32792008, 2020).
tumor (4 papers, 2017 to 2023). "The function of CACNA1B (Cav2.2) is tightly linked to tumor intracellular Ca2+ concentration; targeting intracellular calcium level through VGCCs might represent a novel therapy for NSCLC." (PMID 28127114, 2017). "CACNA1B (Cav2.2) mRNA and protein level were significantly higher in tumorous tissues than in adjacent nontumorous tissues." (PMID 28127114, 2017). "Third, we did not provide a mechanism for the role of CACNA1B (Cav2.2) in tumor development." (PMID 28127114, 2017).
infection (3 papers, 2021 to 2025). The state of being infected such as from the introduction of a foreign agent such as serum, vaccine, antigenic substance or organism. "These events are supported by our results showing that the expression of the mitochondrial pore-forming subunit of calcium voltage-dependent calcium channel subunit (CACNA1B) is upregulated in infection." (PMID 38620036, 2024). "This infection upregulated certain gene expressions, such as ATP5PF, ATP6, COX1, MT-ND5, CYTB, and HIF-1α and downregulated CACNA1B and RYR3 expression." (PMID 41157602, 2025).
movement disorder (3 papers, 2015 to 2021). Neurological conditions resulting in abnormal voluntary or involuntary movement, which may impact the speed, fluency, quality and ease of movement. "The CACNA1B gene codes for the N-type neuronal voltage-gated calcium channels CaV2.2, which may play a role in the development of some movement disorders, including IFD." (PMID 33051750, 2021). "Prior to our study, genetic analysis of the CACNA1B gene in patients with movement disorder was performed in a limited number of studies, by methods not suited for wide gene screening." (PMID 33051750, 2021).
psychiatric disorder (3 papers, 2016 to 2025). A disorder characterized by behavioral and/or psychological abnormalities, often accompanied by physical symptoms. "Intriguingly, a genome-wide analysis has also revealed that CACNA1B along with the CACNA1A gene play a shared effect on 5 major psychiatric disorders, including MDD35." (PMID 28769055, 2017).
genetic disorders (1 paper, 2024). "CACNA1A, the gene encoding CaV2.1, is associated with multiple genetic disorders;7,8 in contrast, there are very few identified human or animal pathological variants of CACNA1B, encoding CaV2.2, which underlies N-type CaV channels." (PMID 38020068, 2024).
hematological malignancy (1 paper, 2022). "This suggests the possibility that CACNA1B could have unrecognized effects on the immune system by disrupting IL-13 and Th17 signaling leading to PANS and an increased risk of hematological malignancy." (PMID 35773312, 2022).
neurodevelopmental disorder (1 paper, 2022). A behavioral and cognitive disorder with onset during the developmental period that involves impaired or aberrant development of intellectual, motor, or social functions.
CACNA1B also shares sentences with these, for which no sentence is quoted: Anxiety (5 papers); depression (3); neurological disorders (3); autism (2); autism spectrum disorder (2); glioma (2); Hypertension (2); memory impairment (2); migraine aura (2); Myoclonus (2); osteoarthritis (2); Alzheimer disease (1); Angelman syndrome (1); autoimmune disease (1); bladder cancer (1); brain cancer (1); cerebellar ataxia (1); Cerebellar atrophy (1); Chorea (1); Cirrhosis (1); Cognitive impairment (1); Cushing syndrome (1); deafness autosomal dominant 10 (1); deafness autosomal recessive 28 (1); delirium (1); Delusion (1); developmental delay (1); diabetes retinopathy (1); diabetic nephropathy (1); diffuse astrocytoma (1).
A further 45 diseases each share a sentence with CACNA1B in 1 paper.